SPINK1 (serine peptidase inhibitor Kazal type 1)
Diseases named in the same sentence as SPINK1 in open-access papers (continued):
Sharing a sentence is not in itself a finding about the gene and the disease.
tumor (continued). "In the UALCAN analysis, the transcription level of SPINK1 was ranked within the top 18 out of all the overexpressed genes in HCC tissues and was significantly higher in the HCC tissue specimens of stage I–III compared to stage IV tumor and grades I–IV (p < 0.05)." (PMID 35924241, 2022). "However, the prevalence of SPINK1 expression did not significantly differ according to the two tumor locations." (PMID 35475132, 2021). "The time required for a 3-fold increase in tumor volume was significantly shorter in the case of DU145/SPINK1 (20.8 ± 3.7 days) than DU145/EV (27.8 ± 4.1 days) xenografts, suggesting that DU145/SPINK1 xenografts were more radioresistant than DU145/EV xenografts." (PMID 34747365, 2021). "Moreover, plasma SPINK1 levels were positively correlated with the extent of tumor hypoxia (R2 = 0.7744), but not with the volume of xenografted tumors (R2 = 0.0658)." (PMID 34747365, 2021). "Serine protease inhibitor Kazal type 1 (SPINK1) is a small secreted protein with dual roles—in the pancreas, it is a protective trypsin inhibitor, while in the context of the tumor microenvironment, it is a cell growth and survival factor that promotes tumor progression." (PMID 30778387, 2019). "More importantly, Kaplan–Meier analysis of PCa patients stratified according to SPINK1 expression in their tumour stromal compartments suggested a significant but negative correlation between stromally expressed SPINK1 and disease-free survival (DFS) of treated patients (P < 0.01, log-rank test)." (PMID 30333494, 2018). "However, four different subsets of tumor cells with distinct transcriptomic patterns based on different gene signatures including epithelial–mesenchymal transition (EMT), cell-cycle and hypoxia, interferon response, and high levels of serine peptidase inhibitor Kazal type 1 (SPINK1) were identified." (PMID 36980203, 2023). "Like Spink1, the preferential overexpression of Elf3 in the CD133+ cells and also in the HCC tumor bulk in both proto-oncogene driven and inflammation-associated HCC tumor models was also apparent, while Elf3 expression was not altered or at a much lesser extent in the regenerating liver." (PMID 38030644, 2023). "However, we could not detect SPINK1 protein circulating in plasma after the ligation, probably because the occlusion prevented SPINK1 proteins from being systemically released from hypoxic tumor cells (data not shown)." (PMID 34747365, 2021). "qPCR analysis confirmed our RNA-seq observations and validated the preferential overexpression of Spink1 in the CD133+ cells and also in the HCC tumor bulk in both HCC tumor models, with expression not altered in the regenerating liver induced by DDC diet or 70% partial hepatectomy." (PMID 38030644, 2023). "Of interest, depletion of hepatic SPINK1 does not diminish the fraction of CD133 liver tumor-initiating/propagating cells though it does reverse the HCC cells to a less stem and more differentiated state as well as decrease the tumor-initiating potential of the HCC cells." (PMID 38030644, 2023).
cancer (93 papers, 2006 to 2026). A tumor composed of atypical neoplastic, often pleomorphic cells that invade other tissues. "Survival analyses across multiple cancer types confirmed the prognostic relevance of resistance-associated genes, including SPINK1, PHGR1, and APOD." (PMID 41724379, 2026). "Serine protease inhibitor Kazal type 1 (SPINK1) is a trypsin kinase inhibitor that has been linked to inflammation, cancer cell proliferation, and carcinogenesis." (PMID 41465391, 2025). "The role of SPINK1 in health and disease is of great interest because SPINK1 activity can exert both beneficial and harmful effects, with aberrant SPINK1 signalling being strongly associated with cancer progression." (PMID 38830931, 2024). "Serine protease inhibitor, Kazal type 1 (SPINK1), a trypsin inhibitor, is closely associated with inflammatory states and the proliferation and metastasis of various cancer cells." (PMID 35479956, 2022). "The impact on cell proliferation and carcinogenesis of SPINK1 by silencing SPINK1 or transfected SPINK1 expression in carcinogen-induced colitis-associated cancer was also evaluated in a mouse model." (PMID 36053457, 2022). "SPINK1 is also associated with PCa; overexpression of SPINK1 is significantly associated with worse cancer-specific survival (CSS) in patients with recurrence after prostatectomy." (PMID 35252264, 2022). "The probands of the BZ2 family and BZ10 family each harbored a pathogenic mutation in SPINK1 and were diagnosed with two primary cancers." (PMID 34567566, 2021). "The SPINK1‐positive cancer cases were reportedly associated with poorer outcomes among ERG‐negative cancer cases." (PMID 35475132, 2021). "The discoverable SPINK1 somatic mutations, expressional signatures, and prognostic significances in various types of cancer have attracted attention as a cancer biomarker in clinical applications." (PMID 33916984, 2021). "The effects of the M2-like phenotype have been more closely linked to cancer progression and metastasis and therefore patient prognosis with SPINK1, LAMC2, IGFBP1, and IL-23A gene expression." (PMID 34732817, 2021). "Consistent with cell viability assay, clonogenic cell survival assays also demonstrated that forced expression of SPINK1 caused radioresistance of cancer cells under not only 20% O2 conditions but also 3% O2 conditions." (PMID 34747365, 2021). "As SPINK1 is subject to frequent overexpression, mutation, amplification, and deep deletion in cancer patients as revealed by the TCGA genomics data, SPINK1 is considered as a potential predictor of disease progression in treatment-naive patients." (PMID 30333494, 2018). "Taken together, the present study for the first time unravels the molecular mechanism underlying SPINK1 overexpression in cancer and thereby opens new avenues for the treatment of SPINK1‐positive malignancies." (PMID 29460395, 2018). "Given the remarkable alterations of cancer cell phenotypes caused by paracrine SPINK1, we next sought to dissect the influence of stromal SPINK1 on cancer cell expression pattern." (PMID 30333494, 2018). "Strikingly, SPINK1 reprograms the expression profile of cancer cells, causing prominent epithelial-endothelial transition (EET), a phenotypic switch mediated by EGFR signaling but hitherto rarely reported for a SASP factor." (PMID 30333494, 2018). "Immunofluorescence (IF) staining of E-cadherin and vimentin in PCa cells essentially confirmed the potency of SPINK1 in causing an EMT in recipient cancer cells." (PMID 30333494, 2018). "Unravelling the mechanisms driving SPINK1‐associated cancer progression may provide valuable insights for the development of novel therapeutic strategies." (PMID 40576306, 2025). "Similarly, serine peptidase inhibitor Kazal type 1 (SPINK1)—often associated with hepatic proliferation and cancer —was elevated across several models, indicating limited specificity for malignancy." (PMID 40862732, 2025).
cancer (continued). "Overexpression of SPINK1 has been linked to poor prognosis in several cancers including PCa." (PMID 38256434, 2024). "Furthermore, high post-CCRT SPINK1 expression was significantly associated with advanced pathological cancer stage and poor CCRT response, which is in line with the previous literature." (PMID 36053457, 2022). "Additionally, the SPINK1 gene has been identified to be associated with many types of cancer, which is mostly attributed to potential epidermal growth factor receptor (EGFR) binding." (PMID 35408828, 2022). "High SPINK1 expression was significantly associated with advanced cancer stage." (PMID 36053457, 2022). "Together, these data support our hypothesis that SPINK1 protein secreted from hypoxic cells had the potential to cause radioresistance of nearby oxygenated cancer cells in a paracrine manner." (PMID 34747365, 2021). "Nonetheless, the molecular mechanism underlying SPINK1 upregulation in cancer is poorly understood." (PMID 29460395, 2018). "However, the vast majority of SPINK1-associated cancer research has been focused on neoplastic cells per se, leaving the host-resident stroma largely overlooked." (PMID 30333494, 2018). "Interestingly, the high abundance of SPINK1 was also exclusively associated with the high levels of ICPs in our analyses, and these ICPs were thought to be involved in the mechanisms by which cancer cells disguise themselves as regular components of the human body." (PMID 35924241, 2022). "Serum levels of SPINK1 has predicted poor prognosis in several cancers, and was in this study the most upregulated protein in EC when compared to HGSC." (PMID 40778374, 2025). "SPINK1 plays an important role in cancer development and progression, with context‐dependent functions." (PMID 40576306, 2025). "Resultant SASP factors induce phenotypic alterations in residual cancer cells, conferring multidrug resistance—e.g., SPINK1 from senescent stroma activates survival pathways in adjacent cancer cells." (PMID 40703657, 2025). "CAS cells expressed cancer‐related genes such as serine peptidase inhibitor Kazal type 1 (SPINK1), CXCL14, carcinoembryonic antigen‐related cell adhesion molecule 5 (CEACAM5) and CEACAM6." (PMID 40824728, 2025). "The IPA summary of contralateral PTE+ cortical astrocytes shows predicted activation of serine peptidase inhibitor Kazal type 1 (SPINK1) general cancer pathway, as well as IL-15 production, KLF4, SOX4 and migration of phagocytes/myeloid cells." (PMID 38600221, 2024). "HCC patients with high SPINK1 expression also enriched for the embryonic stem cell, undifferentiated cancer and HCC stem cell signatures." (PMID 38030644, 2023). "Other SASP factors that facilitate EMT in cancer cells include the pro-inflammatory factors IL-6 and IL-8, Serine protease inhibitor Kazal-type 1 (SPINK1), amphiregulin (AREG), epiregulin (ERPG), and WNT16B." (PMID 37046588, 2023). "Highest enrichment was for genes in SPINK1 General Cancer and the Kinetochore Metaphase Signaling Pathway, which would be concordant with the known role for TPX2 in mitosis." (PMID 37770979, 2023). "Though several members of the SPINK gene family, particularly SPINK1, have been associated with aggressive cancer phenotypes, little is known about SPINK2 in cancer and AML." (PMID 37298647, 2023). "The seven subclusters included alveolar cells, pathological alveolar cells expressing both normal respiratory cell markers (SFTPB, AGR3) and genes related to cancer progression (SPINK1, MET), as well as five cancer subsets." (PMID 36973297, 2023). "Depleting SPINK1 function by neutralizing antibody treatment or in vivo lentivirus-mediated Spink1 knockdown dampens HCC cancer growth and their ability to resist chemotherapy." (PMID 38030644, 2023).
cancer (continued). "Among the upregulated genes we noticed markers those were associated with cancer genesis and development, including SOX4, SPINK1, CEACAM6, KRT8 and KRT18." (PMID 37957625, 2023). "A study illustrated that SPINK1 reprograms cancer cell transcriptome-wide expression to promote EMT and CSC growth." (PMID 37046588, 2023). "SPINK1 general cancer pathway was significantly inhibited by WS-CM only, with a number of metallothionein genes that were significantly upregulated in this pathway." (PMID 35369880, 2022). "This article reviews the role of SPINK1, 2, 4, 5, 6, 7, and 13 in different human cancer processes and helps to identify new cancer treatment targets." (PMID 35223512, 2022). "DNA damage mediates the expression of SPINK1 through nuclear factor-κB (NF-κB) and CCAAT/enhancer-binding protein (C/EBP) in the prostate stromal cell line PSC27, and paracrine SPINK1 promotes the invasiveness and chemotherapy resistance of cancer cells." (PMID 35223512, 2022). "SPINK1 is believed to promote proliferation of cancer cells by inducing EGFR phosphorylation, which results in activation of the mitogen-activated protein kinase (MAPK) pathway." (PMID 35202241, 2022). "Independently of mTOR, Beclin1 was found to be closely associated with the regulation of SPINK1-stimulated autophagy, which more likely shed light on the discovery of a new pathway responsible for SPINK1’s function in colorectal and other types of cancers." (PMID 37305325, 2022). "In vivo, SPINK1 is expressed in the stroma of solid tumors and is routinely detected in the peripheral blood of cancer patients after chemotherapy." (PMID 35223512, 2022). "SPINK1 cancer pathway was predicted to be inhibited in all 3 comparisons of WS-CM vs vehicle control at various dosages." (PMID 35369880, 2022). "SPINK1 reprograms the expression profile of cancer cells, resulting in a significant epithelial−endothelial transition (EET)." (PMID 35223512, 2022). "Several metallothionein genes, including MT1E, MT1G and MT1M were upregulated in the SPINK1 general cancer pathway." (PMID 35369880, 2022). "After 24 h treatment of WS-CM, the top canonical pathways identified in this analysis included the SPINK1 general cancer pathway, nicotine degradation III, melatonin degradation and NRF-2 oxidative stress response." (PMID 35369880, 2022). "Mechanically, because of molecular structural similarity with EGF, the association between SPINK1 and EGFR has been studied in many cancers." (PMID 36053457, 2022). "SPINK1 secreted by hypoxic cells protects surrounding and relatively oxygenated cancer cells from radiation in a paracrine manner." (PMID 35223512, 2022). "MT1M, SLCO1B3, SPINK1, and AKR1B10 were cancer-related genes that were associated with different human diseases, especially in HCC." (PMID 36246599, 2022). "This review aims to shed light on the roles of SPINK1 in cancer and provide guidance and potential directions for scientists in this field." (PMID 33916984, 2021). "The roles of serine protease inhibitor Kazal type 1 (SPINK1) in multiple types of cancers have been significantly documented." (PMID 34595116, 2021). "In the present study, we identified serine peptidase inhibitor Kazal type 1 (SPINK1) as a protein that meets the following 2 criteria: it secreted from hypoxic cancer cells into plasma and induced radioresistance of cancers." (PMID 34747365, 2021). "The ELISA assay demonstrated that the amount of secreted SPINK1 protein in the culture medium significantly increased under severe hypoxic conditions in various cancer cell lines, as expected." (PMID 34747365, 2021). "Because the present study revealed that SPINK1 was secreted from cancer cells under severe hypoxic conditions to plasma, we can expect to be able to utilize SPINK1 as a convenient plasma hypoxia marker." (PMID 34747365, 2021).
cancer (continued). "SPINK1 expression was observed exclusively in an aggressive subgroup of cancers that express TFF3, and SPINK1 was identified as a predictive biomarker for biochemical recurrence in univariate (p = 0.0009) and multivariate (p = 0.0003) analyses." (PMID 33916984, 2021). "SPINK1 overactivity resulted in progression and cancer spread via epidermal growth factor receptor in experimental mouse models." (PMID 33599076, 2021). "Based on these findings, we propose the use of a neutralizing antibody against SPINK1 to overcome the radioresistance of cancers." (PMID 34747365, 2021). "The addition of recombinant SPINK1 induced cancer cell invasion in several human adenoma and carcinoma cells of the colon and breast via phosphoinositide-3-kinase, protein kinase C and Rho-GTPases/Rho kinase-dependent pathways." (PMID 33916984, 2021). "Current evidence emphasizes the urgent need to clarify the prognostic value of SPINK1 and unravel the SPINK1-dependent molecular mechanisms involved in human cancers." (PMID 33916984, 2021). "SPINK1 decreased radiation-induced DNA damage and enhanced radioresistance of cancer cells in EGFR-dependent and nuclear factor erythroid 2–related factor 2–dependent (Nrf2-dependent) manners." (PMID 34747365, 2021). "Subsequent studies indicate that SPINK1 has been detected in multiple types of cancers including bladder, renal, colorectal, prostate, and liver cancers." (PMID 34595116, 2021). "By further addressing these issues, it is expected that the present research can open a new avenue toward the development of a strategy for personalized cancer therapy using SPINK1." (PMID 34747365, 2021). "In this review article, we first integrate the transcriptomic data of different types of cancer with clinical information and recent findings of SPINK1-mediated malignant phenotypes." (PMID 33916984, 2021). "SPINK1 expression in PCa has been associated with poor response to ADT, faster progression to castrate-resistant stage and cancer-associated mortalities, thus highlighting its significance as a biomarker of aggressivity and poor clinical response." (PMID 31959826, 2020). "Under normal physiological condition, SPINK1 inhibits the premature activation of pancreatic proteases, however, multiple reports have observed elevated levels of SPINK1 in cancer tissues, and shown its role in cancer progression." (PMID 31959826, 2020). "SPINK1 is mainly produced in pancreatic acinar cells and is expressed in various cancers and inflammatory states." (PMID 31888570, 2019). "SPINK1 is an important contributor to both increased proliferation and metastasis development in a variety of cancers." (PMID 30778387, 2019). "Unlike in the normal pancreas, in tumors SPINK1 appears to be expressed independently of trypsin, and little is known about the direct target(s) of SPINK1 in the context of cancer." (PMID 30778387, 2019). "BD specifically upregulated tRNA Charging, while RG exclusively activated NGF Signaling and SPINK1 General Cancer Pathway." (PMID 31781116, 2019). "We next explored the mechanism that permits SPINK1 to confer the pro-survival advantage on cancer cells." (PMID 30333494, 2018). "DNA damage causes SPINK1 expression by engaging NF-κB and C/EBP, while paracrine SPINK1 promotes cancer cell aggressiveness particularly chemoresistance." (PMID 30333494, 2018). "It remains elusive why a SPINK1-specific mAb can be more effective than an EGFR-oriented mAb in reducing cancer malignancy." (PMID 30333494, 2018). "Of note, expression of EGF in cancer cells remained unchanged upon exposure to paracrine SPINK1, precluding the possibility of EGFR activation via an autocrine modality by PCa cells." (PMID 30333494, 2018). "MIT induced cleavage of caspase 3, a process that was remarkably weakened by SPINK1 but can be maintained upon elimination of SPINK1 from stromal cells, implying SPINK1 drives cancer resistance largely via a caspase-counteracting mechanism." (PMID 30333494, 2018).